CDK18 (cyclin dependent kinase 18)
Diseases named in the same sentence as CDK18 in open-access papers:
CDK18 is named in the same sentence as 19 diseases in open-access papers, as found by Europe PMC text mining. Sharing a sentence is not in itself a finding about the gene and the disease. The quoted sentences say what the papers report.
Alzheimer disease (3 papers, 2020 to 2022). A progressive, neurodegenerative disease characterized by loss of function and death of nerve cells in several areas of the brain leading to loss of cognitive function such as memory and language. "It has been shown that CDK18 may be involved in Alzheimer’s disease, in the Ataxia Telangiectasia and RAD3-related (ATR)-mediated response to single strand DNA and in cell cycle control." (PMID 32164329, 2020).
breast carcinoma (3 papers, 2018 to 2025). "CDK18 is also an important regulator of DNA replication stress signaling also in breast cancer where elevated protein levels of CDK18 were associated with increased sensitivity to replication stress-inducing chemotherapeutic agents." (PMID 39800748, 2025). "Similar data have been observed in breast cancer, where high levels of CDK18 were associated with increased sensitivity to replication stress-inducing chemotherapeutic agents." (PMID 38951876, 2024). "Strikingly, breast cancers exhibiting elevated CDK18 mRNA expression were associated with a poorer response to the commonly used replication stress-inducing chemotherapeutic agents 5-FU, cyclophosphamide and methotrexate (n = 416, Log Rank -3.901, p = 0.04)." (PMID 30034634, 2018). "On the contrary, breast cancers with increased CDK18 mRNA was associated with poor response to chemotherapeutic agents, inducing DNA replication stress, suggesting that CDK18 mRNA and protein levels are differently regulated with hypothetically distinct predictions on patients prognosis." (PMID 39800748, 2025). "From 162 studies representing over 45,000 samples, CDK18 gene amplification (due to copy number variance gain) was vastly more prevalent than deletions or mutations, with 4 out of the top 5 incidences of reported CDK18 amplification occurring in breast cancer cohorts." (PMID 30034634, 2018). "Based on these findings, we next investigated whether alterations in CDK18 at the transcriptomic level within breast cancer cohorts might be associated with various aspects of tumour biology and/or patient prognosis." (PMID 30034634, 2018). "For example, we observed opposite survival associations between heightened CDK18 mRNA and protein expression in two large breast cancer cohorts (>1600 patients each), although such discrepancies may in part due to the fact that mRNA and protein expression levels often do not correlate." (PMID 30034634, 2018). "Indeed, CDK18's role in facilitating efficient cellular responses to replication stress make it an attractive therapeutic target in many cancers, including in breast cancer where strong associations between oestrogen receptor signalling, cell proliferation and replication stress are emerging." (PMID 30034634, 2018). "The associations between CDK18 amplification and/or mRNA expression levels with breast cancer patient survival prompted us to investigate CDK18 protein expression within breast cancers in relation to clinicopathological phenotypes." (PMID 30034634, 2018). "Here we report our analysis of differential CDK18 mRNA and protein expression levels in relation to clinicopathological parameters within human breast cancers utilising large independent breast cancer clinical cohorts." (PMID 30034634, 2018). "Our data therefore add to the growing interest in the role of CDKs within breast cancer biology and clinical management strategies, and suggest that further study of CDK18 within other cancers is warranted." (PMID 30034634, 2018). "Using these optimised IHC conditions, we proceeded to investigate CDK18 protein expression in the Nottingham Tenovus series of 1650 breast cancers for which detailed clinicopathological parameters and various molecular markers have been previously defined." (PMID 30034634, 2018). "To further understand our findings in the clinical cohorts, we next investigated the consequences of increased CDK18 expression at a molecular level using breast cancer cell culture models." (PMID 30034634, 2018). "Similar to the commercial breast cancer TMAs, we observed nuclear as well as cytoplasmic staining of CDK18, however, nuclear expression was rare and cytoplasmic expression was more common within these samples." (PMID 30034634, 2018). "CDK18 protein expression was evaluated in 1650 breast cancers and correlated to clinicopathological parameters and survival outcomes." (PMID 30034634, 2018).
breast carcinoma (continued). "Similar analyses were carried out for genetic and transcriptomic changes in CDK18 within several publically available breast cancer cohorts." (PMID 30034634, 2018). "In the current study, we have investigated the clinicopathological and functional significance of CDK18 expression levels in breast cancers." (PMID 30034634, 2018). "We also find that breast cancers exhibit higher levels of both CDK18 mRNA and protein compared with normal breast tissue." (PMID 30034634, 2018). "CDK18 has been reported to be overexpressed in gastric cancer, where it appears to promote cancer cell proliferation and reduce T-cell tumor infiltration, pituitary adenomas and breast cancer." (PMID 39800748, 2025). "High CDK18 protein expression was linked to the basal subtype of breast cancer and improved patient survival in estrogen receptor (ER)-negative breast cancers treated with chemotherapy." (PMID 38951876, 2024). "If alterations in CDK18 expression are indeed beneficial to tumour development, our data suggest that this may be a complex relationship in breast cancer." (PMID 30034634, 2018). "Overall, these data suggest that subsequent CDK18 protein expression levels and/or cellular activity might be important for aspects breast cancer biology and treatment outcomes." (PMID 30034634, 2018). "We also report our phenotypic characterisation of deactivated dCRISPR-mediated genetically engineered breast cancer cell models that over express the endogenous CDK18 gene, and how these phenotypes may relate to our findings in breast cancer patients." (PMID 30034634, 2018). "Additionally, we used a deactivated CRISPR/Cas9 approach (dCRISPR) to elucidate the molecular consequences of heightened endogenous CDK18 expression within breast cancer cells." (PMID 30034634, 2018). "Finally, we assessed the phenotypic consequences of the reduced replication stress signalling in the CDK18 activation clones by carrying out clonogenic survival assays using the breast cancer chemotherapeutic agents 5-FU and Methotrexate." (PMID 30034634, 2018). "Indeed, we found that CDK18 protein expression was significantly correlated with expression levels of DNA repair factors and cell cycle checkpoint regulators within human breast cancer samples." (PMID 30034634, 2018). "Indeed, CDK18 amplification was prevalent in the majority of all the reported breast cancer cohorts (representing ~6000 samples), ranging from ~5–26%, with an average amplification of 11.3%." (PMID 30034634, 2018). "Overall, the data from the CDK18 activation clones is consistent with our findings in breast cancer clinical cohorts, where elevated levels of endogenous CDK18 protein expression confers an improved repose to chemotherapeutic agents that induce high levels of replication stress." (PMID 30034634, 2018). "To achieve this, we employed a deactivated CRISPR/Cas9 system to up-regulate the endogenous CDK18 promoter in MDA-MB-231 breast cancer cells due to its phenotypic comparison with difficult to treat breast cancers e.g. triple negative status and intermediate response to chemotherapy." (PMID 30034634, 2018). "Collectively, these data suggest that CDK18 expression could potentially predict response to chemotherapeutic agents, and may influence certain aspects of breast cancer biology." (PMID 30034634, 2018). "Our findings reveal that amplification of the CDK18 gene locus and CNV gains are widespread across human cancers, with a particularly high prevalence in breast cancers." (PMID 30034634, 2018). "As the largest CDK18 gene amplification occurs within METABRIC dataset, which is the most comprehensive breast cancer cohort for which detailed clinicopathological information is known, we further interrogated CDK18 mRNA expression levels within this cohort." (PMID 30034634, 2018).
glioblastoma (3 papers, 2019 to 2024). The most malignant astrocytic tumor (WHO grade IV). "Previously, MYC amplification has been discovered to promote homologous recombination via targeting CDK18 in glioblastoma." (PMID 33448691, 2020). "Here, the authors show that MYC amplified glioblastomas are sensitive to PARP inhibition due to CDK18 repression, which impairs ATR regulated homologous recombination repair, and that ATR inhibition sensitises glioblastomas to PARP inhibition." (PMID 31266951, 2019). "CDK18 knockdown or ATR inhibition, in glioblastoma stem-like cells (GSCs), suppressed HRD and conferred PARPi sensitivity." (PMID 38951876, 2024). "Interestingly, CDK18 also plays a role in ATR-mediated Homology-Directed Repair (HDR), in glioblastoma." (PMID 38951876, 2024). "We show that MYC or MYCN amplification in patient-derived glioblastoma stem-like cells (GSCs) generates sensitivity to PARPi via Myc-mediated transcriptional repression of CDK18, while most tumors without amplification are not sensitive." (PMID 31266951, 2019).
glioma (3 papers, 2020 to 2024). A benign or malignant brain and spinal cord tumor that arises from glial cells (astrocytes, oligodendrocytes, ependymal cells). "Interestingly, this induction of CDK18 led to growth arrest and cell death in the glioma cells." (PMID 38951876, 2024). "CDK17, on the other hand, shows its highest expression in Low-Grade Glioma (LGG) and CDK18 reaches its peak in renal clear cell carcinoma (KIRC)." (PMID 38951876, 2024). "For example, Myc targeted CDK18 affects the interaction of ATR-RAD9 and ATR-ETAA1, and promotes ATR activation, thus promoting homologous recombination and PARP inhibitor resistance in glioma." (PMID 37349788, 2023).
gastric cancer (2 papers, 2018 to 2020). A primary or metastatic malignant neoplasm involving the stomach. "Loss of CDK18 may lead to dysregulation of cell-cycle check-point increasing genomic instability and development of gastric cancer." (PMID 30212456, 2018). "With an attempt to further explore the correlation between CDK18 and gastric cancer, the expression of CDK18 in gastric cancer tissues and cells was measured, and the results showed that the expression of CDK18 was increased in gastric cancer tissues and cells." (PMID 32715641, 2020).
adenoma (1 paper, 2022). A neoplasm arising from the epithelium. "CDK9 and CDK18 were upregulated in NR5A1-adenomas, whereas CDK4 and CDK7 were upregulated in POUF1-adenomas." (PMID 35260162, 2022).
cutaneous T-cell lymphoma (1 paper, 2024). "Initial indications of CDK18 potential involvement in tumor progression emerged from studies showing that silencing CDK18 inhibited the growth of cutaneous T-cell lymphoma cells, suggesting that CDK18 may play a role in promoting their growth." (PMID 38951876, 2024).
diabetes (1 paper, 2025). "CDK18 also shows slightly higher expression in diabetic pancreatic islets compared to normal islets, supporting a possible link between CDK18 expression and the onset/development of diabetes." (PMID 39800748, 2025).
invasive breast carcinoma (1 paper, 2019). A carcinoma that infiltrates the breast parenchyma. "CDK18 is amplified in about 20% of invasive breast carcinomas, 12% of metastatic prostate cancers, and 5% serous ovarian cancers (cBioPortal), suggesting its role as a cancer driver." (PMID 31266951, 2019).
type 2 diabetes (1 paper, 2024). "CDK18 has been also observed to have slightly higher expression in diabetic pancreatic islets vs. normal islets, and genome-wide association studies have hinted at a possible link between CDK18 polymorphism and type 2 diabetes, particularly in African Americans." (PMID 38951876, 2024).
cancer (8 papers, 2017 to 2025). A tumor composed of atypical neoplastic, often pleomorphic cells that invade other tissues. "Furthermore, CDK14, CDK16, CDK18 and cyclin Y have all been linked to cancer cell proliferation, migration or cancer drug resistance." (PMID 28057719, 2017). "Overall, the available data suggest that CDK18 has multifaceted functions in human cancer and can act either as oncogene or as tumor suppressor, depending on the specific tumor type and context." (PMID 38951876, 2024). "Relatively more studies have attempted to address the role of CDK18 in cancer progression, compared to CDK17." (PMID 38951876, 2024). "CDK18 has been reported to be overexpressed in gastric cancer, where it appears to promote cancer cell proliferation and reduce T cell tumor infiltration." (PMID 38951876, 2024). "Further research is needed to fully understand the complexities of CDK18 roles in different cancer types and determine its potential as a biomarker and/or therapeutic target." (PMID 38951876, 2024). "In the second stage, the expression levels turned out to be similar in cancer versus normal blood for most genes, except for CDK18 and CCND1 which paradoxically turned out to be downregulated in cancer blood." (PMID 32013938, 2020). "Development of pharmacological inhibitors of CDK18 should afford cancer therapeutics that would enhance the efficacy of PARPi and DNA-damaging agents." (PMID 31266951, 2019). "As part of our interest in a potential role for CDK18 in cancer biology and putative therapeutic target, we interrogated CDK18 genomic alterations in a range of published cancer genome databases." (PMID 30034634, 2018). "It would therefore be interesting to further investigate potential relationships between endogenous levels of replication stress and CDK18 expression in other cancer cohorts." (PMID 30034634, 2018). "This implies that CDK18 role may be context-dependent, and its effects on cancer progression can differ based on the specific type of cancer and microenvironmental conditions." (PMID 38951876, 2024). "However, the effects of CDK18 in different cancer types can vary." (PMID 38951876, 2024). "Although PCTAIRE1 has been found to be upregulated in many cancers, so far there is no such data for CDK18." (PMID 32013938, 2020). "The downregulation of CDK18 RNA in cancer blood (metastatic and non-metastatic grouped together) compared to normal was significant with p value = 0.001, whereas CCND1 was downregulated with p = 0.039." (PMID 32013938, 2020).
tumor (8 papers, 2012 to 2025). "This suggests that CDK18 may play a role in regulating cell adhesion and migration, processes often associated with tumor spreading." (PMID 38951876, 2024). "As such, CDK18 expression levels may provide more significant biological roles in different tumour populations depending on the underlying levels of replication stress and functional status of the various DNA damage response & cell cycle checkpoint machinery." (PMID 30034634, 2018). "In MGG4 tumors, CDK18 overexpression slowed tumor growth and abrogated PARPi responsiveness." (PMID 31266951, 2019). "CDK18 knockdown in BT74 slowed tumor growth but rendered tumors responsive to PARPi." (PMID 31266951, 2019). "One possible way in which differential CDK18 expression may arise in human tumours is as a result of elevated replication stress within the cancerous cells." (PMID 30034634, 2018). "Intriguingly, a recent report identified CNV gains and increased CDK18 mRNA expression in several distinct tumour populations from within a diffuse intrinsic pontine glioma, suggesting a selection preference for such genetic alterations to CDK18 expression during tumour development." (PMID 30034634, 2018). "Our original findings in the METABRIC suggested that high mRNA levels of CDK18 were associated with poor survival, which was also true for in ER-, but not ER+ tumours." (PMID 30034634, 2018). "In the sub-group that received CMF based chemotherapy, there was a similar trend with better survival in patients with high cytoplasmic CDK18 expressing tumours (p = 0.07), but not in patients who received anthracycline-based chemotherapy." (PMID 30034634, 2018). "However, elevated CDK18 mRNA expression (above median) was associated with reduced patient survival across the whole cohort (n = 1975, Log Rank -5.139, p = 0.02), which was also true for ER- tumours (n = 437, Log Rank –3.729, p = 0.05), but not for ER+ tumours." (PMID 30034634, 2018). "Consistent with CDK18 mRNA expression, CDK18 protein expression did not influence survival within ER+ tumours." (PMID 30034634, 2018). "Interestingly, increased CDK18 expression was associated with cancerous tissue compared to healthy and non-cancerous adjacent tissue (OR = 9.655, p =< 0.001), although CDK18 expression did not continue to increase beyond grade 2 tumours within these tissue microarrays." (PMID 30034634, 2018). "Moreover, CDK18/CDK19 inhibition suppressed the tumour-promoting activities of fibroblasts and decreased intra-tumoural blood supply in an AR-driven patient-derived xenograft model, the latter finding suggesting that these kinases enhance tumour angiogenesis." (PMID 40163908, 2025). "The PA showed alterations in CDK18 and THY1 mRNA isoforms which could be tumor specific." (PMID 33261069, 2020). "The vast majority of genes were equally expressed in tumor and non-tumoral, control pituitary glands, including CCNL1, CCNE2, CCNB2, CCNA1, CDK18, CDK19 and CDK20." (PMID 35260162, 2022).
CDK18 also shares sentences with these, for which no sentence is quoted: ataxia telangiectasia (1 paper); colorectal cancer (1); coronary artery disease (1); IMAGe syndrome (1); infection (1); metastatic prostate carcinoma (1); serous ovarian cancers (1).